OR2T35 (olfactory receptor family 2 subfamily T member 35 (gene/pseudogene))
Description:
Odorant receptor.
Tractability: Antibody: UniProt places it where antibodies can reach, with medium confidence; UniProt predicts a signal peptide or a membrane-spanning region; its Gene Ontology location is reachable by antibodies, with medium confidence.
Gene: Protein-coding gene on chromosome 1 (248,636,356 to 248,645,278, reverse strand). Ensembl gene ENSG00000177151.
Subcellular location: Cell membrane
Pathways (Reactome):
Sensory Perception: Expression and translocation of olfactory receptors
Gene Ontology:
Molecular function: olfactory receptor activity; G protein-coupled receptor activity
Biological process: detection of chemical stimulus involved in sensory perception of smell; G protein-coupled receptor signaling pathway
Cellular component: plasma membrane; membrane
Genetic constraint (gnomAD): Missense variants: 17 observed, 34.93 expected, observed/expected ratio (o/e) 0.49, 90% interval 0.33 to 0.73. Synonymous variants: 6 observed, 13.17 expected, observed/expected ratio (o/e) 0.46, 90% interval 0.25 to 0.9.
Homologues: Orthologues: dog OR2T2 (88% identical), rat Or2t35 (85% identical), mouse Or2t35 (83% identical). Paralogues in human: OR2T2 (99% identical), OR2T11 (68% identical), OR2T27 (66% identical), OR2T1 (65% identical), OR2T29 (63% identical), OR2T5 (63% identical), OR2T4 (61% identical), OR2T10 (60% identical), OR2T6 (60% identical), OR2T3 (58% identical), OR2T34 (57% identical), OR2T33 (53% identical), and 80 more.
Diseases named in the same sentence as OR2T35 in open-access papers:
OR2T35 is named in the same sentence as 3 diseases in open-access papers, as found by Europe PMC text mining. Sharing a sentence is not in itself a finding about the gene and the disease. The quoted sentences say what the papers report.
tumor (1 paper, 2017). "We identified four novel genes, KRTAP4-5, OR2T35, GPRIN1, and MRPL18, of unknown function in tumor progression and metastasis." (PMID 28249600, 2017).
OR2T35 also shares sentences with these, for which no sentence is quoted: ovarian carcinoma (1 paper); serous ovarian cancer (1).